HTRA3 (HtrA serine peptidase 3)
Diseases named in the same sentence as HTRA3 in open-access papers (continued):
Sharing a sentence is not in itself a finding about the gene and the disease.
colorectal cancer (3 papers, 2020 to 2022). A primary or metastatic malignant neoplasm that affects the colon or rectum. "The expression of HTRA3 in the peritumor stroma of patients with stage II colorectal cancer is associated with high-grade tumor budding, which may be a new marker of poor prognosis." (PMID 33425760, 2020). "Here we demonstrated that CGI hypermethylation of FIGN, HTRA3, BDNF, HCN4 and STAC2 in colorectal cancer is associated with patient progression to metastasis, identifying them as putative future biomarkers for CRC progression." (PMID 32971738, 2020). "On the other hand, HTRA3 is highly expressed in oral squamous cell carcinoma, thyroid cancer and colorectal cancer, and the acquisition of invasive phenotype in oral squamous cell carcinoma and colorectal tumor is closely related to poor prognosis." (PMID 33425760, 2020). "In colorectal cancer, researchers identified that HTRA3 could be expressed by tumor cells and peritumoral stromal cells." (PMID 36387901, 2022). "HTRA3 is highly expressed in the stroma of the invasive front of colorectal cancer." (PMID 33425760, 2020). "In addition, the expression of HTRA3 in the peritumor stroma of patients with stage II colorectal cancer is related to high grade tumorous budding, which may be a new marker of poor prognosis." (PMID 33425760, 2020). "In addition, the hypermethylation of FIGN, HTRA3, BDNF, HCN4 and STAC2 could be utilised in primary tumour as biomarkers of colorectal cancer prognosis." (PMID 32971738, 2020). "Statistical association between poor survival and hypermethylation of CGI was established in FIGN (p = 0.030), HTRA3 (p = 0.009), BDNF (p = 0.002), HCN4 (p = 0.018) and STAC2 (p = 0.007) and may be used as potential markers for metastasis progression in colorectal cancer." (PMID 32971738, 2020).
gastric cancer (3 papers, 2020 to 2023). A primary or metastatic malignant neoplasm involving the stomach. "High expression of HTRA3 was associated with advanced clinical stage and indicated poor overall survival proportion in gastric cancer." (PMID 36387901, 2022). "A recent study showed that HtrA3 plays a vital role in the progression of gastric cancer and that there was a positive correlation between HtrA3 expression and the abundances of innate immunocytes (natural killer cells, macrophages etc.)." (PMID 37842043, 2023). "Therefore, we expanded the number of paired samples to verify mRNA and protein differential expression of HTRA3 in gastric cancer tissues and cell lines." (PMID 33425760, 2020). "HtrA serine peptidase 3 (HTRA3) participates in multiple signal pathways and plays an important regulatory role in various malignancies; however, its role on prognosis and immune infiltrates in gastric cancer (GC) remains unclear." (PMID 33425760, 2020).
heart failure (3 papers, 2022 to 2024). Inability of the heart to pump blood at an adequate rate to meet tissue metabolic requirements. "In this study, we demonstrate that cardiac fibroblasts are critically involved in the development of heart failure by inducing not only cardiac fibrosis but also cardiomyocyte secretory phenotype through Htra3-TGF-β-IGFBP7 axis." (PMID 35672400, 2022). "To understand how activation of TGF-β signaling affects cardiomyocytes and leads to heart failure, we performed scRNA-seq of cardiomyocytes isolated from WT and Htra3 KO mice at 2 weeks after TAC or sham surgery." (PMID 35672400, 2022). "Htra3-induced TGF-β repression might be a therapeutic approach for heart failure." (PMID 35672400, 2022). "Additional mild pressure overload by TAC rapidly induced severe heart failure in Htra3 KO mice but not in WT mice." (PMID 35672400, 2022). "Pressure overload downregulates expression of Htra3 in cardiac fibroblasts and activated TGF-β signaling, which induces not only cardiac fibrosis but also heart failure through DNA damage accumulation and secretory phenotype induction in failing cardiomyocytes." (PMID 35672400, 2022).
oral squamous cell carcinoma (3 papers, 2016 to 2022). "Evidence from studies has shown that high expression of HTRA3 was correlated with poor prognosis in oral squamous cell carcinoma." (PMID 35445008, 2022). "On the other hand, a study in oral squamous cell carcinoma indicated that HTRA3 mRNA and protein levels were elevated specifically in invasive tumors compared with premalignant lesions." (PMID 27166271, 2016). "HTRA3 was related to the acquisition of invasive phenotype of oral squamous cell carcinoma and may be a potential prognostic indicator of oral cancer." (PMID 33425760, 2020).
thyroid cancer (3 papers, 2020 to 2022). "Kaplan–Meier plots suggested that high expression of PCOLCE2 and HTRA3 were associated with poor prognostic outcomes of thyroid cancer patients in TCGA." (PMID 36387901, 2022). "Secondly, the expression of PCOLCE2 and HTRA3 were decreased in thyroid tumor and indicated favorable prognosis for thyroid cancer patients, which is contradictory to the conventional perception." (PMID 36387901, 2022). "Survival analysis suggested that high expression level of PCOLCE2 and HTRA3 were related to poor overall survival results for thyroid cancer patients." (PMID 36387901, 2022). "Here, we showed that PCOLCE2 and HTRA3 were mainly expressed by fibroblasts in thyroid cancer and decreased in tumor tissues." (PMID 36387901, 2022). "recent studies have also shown that HTRA3 was highly expressed in thyroid carcinoma and related to the occurrence of thyroid cancer." (PMID 33425760, 2020). "However, low expression of PCOLCE2 and HTRA3 suggested favorable clinical outcomes for thyroid cancer patients." (PMID 36387901, 2022). "Univariate Cox regression analysis was further applied to assess the prognostic value of DEFRGs, and we found that 4 DEFRGs (APOE, P = 0.004; TSC22D1, P = 0.025; TIMP1, P = 0.029; HTRA3, P = 0.007) may act as independent factors for overall survival of thyroid cancer." (PMID 36387901, 2022). "First, we verified the expression of 9 immune-related prognostic factors, AKAP12, APOC1, TIMP3, ADAMTS9, ANK2, HTRA3, SYNDIG1, ​​ADAMTS5 and DACT1, in 11 thyroid cancer cell lines in the CCLE database." (PMID 36591507, 2022). "Here, we performed LASSO analysis and identified 6 critical fibroblasts related factors (PCOLCE2, APOD, APOE, TIMP1, HTRA3 and MT1A) and calculated the fibrosis scores based on their expression in patients with thyroid cancer." (PMID 36387901, 2022).
colon cancer (2 papers, 2020 to 2022). "Specifically, in colon cancer, low immunohistochemical expression of HtrA3 has been associated with invasion and poor prognosis." (PMID 32971738, 2020). "The low expression of HtrA3 in colon cancer tissues could be linked to a repression by methylation, which would be interesting for further investigations." (PMID 32971738, 2020).
colorectal tumor (2 papers, 2020). "In the present study we evaluated the expression of the HTRA1-3 genes, encoding human HtrA serine proteases HtrA1, HtrA2, and HtrA3 isoforms (HtrA3L and HtrA3S), at both mRNA and protein levels, in colorectal tumor tissue and unchanged colorectal mucosa of the CRC patients." (PMID 32486357, 2020). "In colorectal tumor tissues, HtrA1 and HtrA3 were detected in both tumor cells and stromal compartment." (PMID 32486357, 2020). "We also analyzed the expression of the HTRA3 gene in colorectal tumors." (PMID 32486357, 2020).
lung adenocarcinoma (2 papers, 2020 to 2021). A carcinoma that arises from the lung and is characterized by the presence of malignant glandular epithelial cells. "Just as reported, LINC00467 promoted lung adenocarcinoma proliferation, migration and invasion by binding with EZH2 and repressing HTRA3 expression." (PMID 33996559, 2021).
thyroid tumor (2 papers, 2022 to 2023). A benign or malignant neoplasm affecting the thyroid gland. "Immunohistochemical indicated that APOE stained highly in thyroid tumor, while HTRA3 and MT1A showed the reverse staining results." (PMID 36387901, 2022). "The protein levels of HTRA3 and MT1A were significantly attenuated, but APOE protein level was increased in thyroid tumor." (PMID 36387901, 2022).
acute lymphoblastic leukemia (1 paper, 2021). Leukemia with an acute onset, characterized by the presence of lymphoblasts in the bone marrow and the peripheral blood. "For instance, HtrA3 is downregulated in B-cell and T-cell acute lymphoblastic leukemia and acute myeloid leukemia, yet HtrA3 is significantly increased in acute lymphoblastic leukemia where chromosome translocation has occurred at 11q23/MLL or TCF3/PBX1." (PMID 34639128, 2021).
Alzheimer disease (1 paper, 2024). A progressive, neurodegenerative disease characterized by loss of function and death of nerve cells in several areas of the brain leading to loss of cognitive function such as memory and language. "Htra3 is a gene involved in intracellular protein hydrolysis and a paralog of Htra1 and was identified as a biomarker for Alzheimer’s disease in mice through proteomic analysis." (PMID 39799000, 2024).
asthma (1 paper, 2020). "We suggest that the higher level of HTRA3 and HTRA1 in children with atopy and asthma might be connected with their known interactions with TGFβ." (PMID 32560402, 2020).
brittle cornea syndrome (1 paper, 2025). Brittle cornea syndrome is a form of Ehlers-Danlos syndrome characterized by a severe ocular manifestations due to extreme corneal thinning and fragility with rupture in the absence of significant trauma, and progression to blindness. "HTRA3 (High temperature requirement A, Serine Peptidase 3) is a serine protease involved in matrix remodelling while ZNF469 (Zinc-finger protein 469) regulates the expression of extracellular matrix components and its mutations have been linked to brittle cornea syndrome." (PMID 40716152, 2025).
cardiac hypertrophy (1 paper, 2022). "Compared with wild-type (WT) control mice, Htra3 KO mice showed cardiac hypertrophy with enlarged cardiomyocyte size even in the absence of pressure overload without change of blood pressure." (PMID 35672400, 2022).
hepatocellular carcinoma (1 paper, 2020). A malignant tumor that arises from hepatocytes. "Studies have shown that FIGN is overexpressed in human hepatocellular carcinomas promoting hepatocyte invasion HTRA3 (high temperature requirement A3) is a member of the HtrA family and is a proapoptotic protease shown to promote drug-induced cytotoxicity and proposed to have an antitumour effect." (PMID 32971738, 2020).
intrauterine growth restriction (1 paper, 2021). "Furthermore, serum levels of HtrA3 at 11–13 weeks as well as at 15 weeks of gestation are significantly lower in pregnancies that proceed with subsequent intrauterine growth restriction (IUGR)." (PMID 34639128, 2021).
kidney injury (1 paper, 2021). Trauma to the kidney. "Like ATF3, HtrA3 proteins also play a protective role in ischemia–reperfusion kidney injury." (PMID 33462352, 2021).
leukemia (1 paper, 2022). A malignant (clonal) hematologic disorder, involving hematopoietic stem cells and characterized by the presence of primitive or atypical myeloid or lymphoid cells in the bone marrow and the blood. "By contrast, no sign of leukemia was observed in six mice transplanted with ITD/ITD lin− cells with Lin28a knockdown 4 months after transplantation, indicating a cooperative effect between Htra3, Lin28a, and ITD/ITD in AML induction." (PMID 34732858, 2022).
liver cancer (1 paper, 2022). An epithelial or non-epithelial malignant neoplasm that arises from the liver. "Moreover, TMAO upregulates POSTN, NAPB, LAYN, and HTRA3 in liver cancer, and high expression levels of these genes are closely associated with suppression of the immune microenvironment and patient survival outcomes in liver cancer." (PMID 35676936, 2022). "Interestingly, higher expression of POSTN (OS HR = 1.63, 95% CI = 1.13–2.33, p = 0.0076; DSS HR = 1.8, 95% CI = 1.11–2.93, p = 0.016), LAYN (DSS HR = 1.61, 95% CI = 1.02–2.55, p = 0.039) and HTRA3 (OS HR = 1.53, 95% CI = 1.08–2.17, p = 0.015) were associated with poorer outcomes in liver cancer." (PMID 35676936, 2022). "Overall, the survival analysis based on the DEGs suggests that the expression of POSTN, HTRA3, LAYN, AFM and AANAT are associated with the outcomes of patients with liver cancer." (PMID 35676936, 2022). "Upregulation of POSTN, LAYN and HTRA3 and downregulation of AANAT and AFM were positively related to poorer overall survival in human liver cancer." (PMID 35676936, 2022).
myocardial infarction (1 paper, 2022). Gross necrosis of the myocardium, as a result of interruption of the blood supply to the area, as in coronary thrombosis. "Htra3-regulated induction of spatio-temporal cardiac fibrosis and cardiomyocyte secretory phenotype are observed specifically in infarct regions after myocardial infarction." (PMID 35672400, 2022). "To elucidate how Htra3 spatially regulates cardiac remodeling, we investigated the role of Htra3 in myocardial infarction (MI) model." (PMID 35672400, 2022).
oral cancer (1 paper, 2020). "HTRA3 may be related to the acquisition of invasive phenotype of and may be a potential prognostic indicator of oral cancer." (PMID 33425760, 2020).
placental insufficiency (1 paper, 2017). Failure of the placenta to deliver an adequate supply of nutrients and oxygen to the fetus. "We further demonstrated that in women serum levels of HtrA3 during early pregnancy were significantly lower in IUGR pregnancies, establishing an association between lower HtrA3 levels and placental insufficiency in the human." (PMID 28676687, 2017). "Future studies are warranted to establish the causal role of lower HtrA3 in human placental insufficiency." (PMID 28676687, 2017). "Furthermore, in pregnant women, serum levels of HtrA3 during early pregnancy were significantly lower in those who subsequently developed IUGR, establishing an association between lower HtrA3 levels early in pregnancy and placental insufficiency in the human." (PMID 28676687, 2017). "Strikingly, HtrA3 deletion in the mother but not in the fetus, resulted in placental insufficiency and intra-uterine fetal growth restriction (IUGR)." (PMID 28676687, 2017).
pregnancy disorder (1 paper, 2014). A disorder that is related to pregnancy. "Since HtrA1, HtrA3 and HtrA4 share identical domain organization, our results establish important foundations for developing potential therapeutics to target these HtrA proteins specifically for the treatment of a number of diseases, including cancer and pregnancy disorders." (PMID 25248123, 2014).
tumor (27 papers, 2014 to 2024). "HTRA3 dysregulation has also been implicated in many malignancies, with HtrA3 being proposed as a tumour suppressor." (PMID 34639128, 2021). "The study investigated HTRA3 expression in tumor tissues and its association with immune infiltrates, and determined its prognostic roles in GC patients." (PMID 33425760, 2020). "Disturbances in HtrA3 action were also associated with oncogenesis and this protease is suggested to be a potential tumor suppressor." (PMID 32486357, 2020). "Indeed, high expression of HTRA3 in CRC tumor stroma was associated with adverse outcomes such as high tumor budding." (PMID 35445008, 2022). "Similarly, we demonstrated a positive association between HTRA3 and the inflammatory tumor microenvironment." (PMID 35676936, 2022). "Therefore, alterations of HtrA3 in cancer are tissue-specific, and the underlying molecular changes associated with HtrA3 need to be investigated in different tumours." (PMID 34639128, 2021). "Moreover, the underlying functions and mechanisms of HTRA3 in tumor progression and tumor immunology are still unclear." (PMID 33425760, 2020). "Thus, the underlying mechanism by which HTRA3 suppresses tumor cell motility clearly warrants further investigation in confirmatory studies and in varied tumor types." (PMID 27166271, 2016). "S100a8 hallmarks inflammatory TAMs, and Htra3 function as a tumor suppressor by stimulating apoptosis in LC." (PMID 38245882, 2024). "Some studies suggest that HTRA3 functions as a pro-apoptotic protein and as a tumor suppressor in the pathogenesis of cancer." (PMID 37185732, 2023). "Consistent with a report demonstrating Htra3 as an inhibitor of TGF-ß signaling (a tumor suppressor in human hematologic malignancies), we also found that overexpression of Htra3 in 32D murine myeloid cells significantly inhibited TGF-ß-induced apoptosis." (PMID 34732858, 2022). "A previous study reported that HTRA3 is a pro-apoptotic protein which also suppresses tumor formation." (PMID 35445008, 2022). "Firstly, the expression level of HTRA3 between normal hepatic samples and tumor tissues was analyzed according to TCGA database." (PMID 34217320, 2021). "The difference is that HTRA3 mRNA levels gradually decline as tumor grade increases, while HTRA1 mRNA levels immediately decrease with the increase in early G1EC, then remain at a lower level, and then dynamic change with the increase in tumor grade." (PMID 34563186, 2021). "The human HtrA3 protease is involved in development and progress of many physiological events, including placentation, stimulation of apoptosis and considered as a tumor suppressor." (PMID 33462352, 2021). "The high expression of HTRA3 in tumor core was significantly correlated with the decrease of 5-year overall survival rate." (PMID 33425760, 2020). "Low expression of high temperature requirement A3 (HTRA3) has been reported to promote tumorigenesis, diminish the effects of anti-tumor treatments, and correlate with a malignant phenotype." (PMID 27166271, 2016). "Further, due to its proteolytic activity, HTRA3 is able to digest some components of the extracellular matrix, which facilitates tumor invasion and metastasis." (PMID 27166271, 2016). "In the multivariate Cox proportional hazards regression model, expression of HTRA3 protein, gender, smoking status, pathology and tumor stage were used as covariates." (PMID 27166271, 2016). "HtrA3 is thus proposed to be a tumor suppressor and a potential therapeutic target in the cancer treatment." (PMID 26110759, 2015). "Human HtrA3 protease, which induces mitochondria-mediated apoptosis, can be a tumor suppressor and a potential therapeutic target in the treatment of cancer." (PMID 26110759, 2015).